CRH (corticotropin releasing hormone)
Diseases named in the same sentence as CRH in open-access papers (continued):
Sharing a sentence is not in itself a finding about the gene and the disease.
pituitary adenoma (continued). "Two negative cases included one patient with a pituitary adenoma sized between 6 and 10 mm but discordant CRH test and HDDST and another one with negative imaging and concordant tests." (PMID 34699044, 2022). "About 80% of CS cases are due to ACTH secretion by a pituitary adenoma, about 20% are due to ACTH secretion by nonpituitary tumors (ectopic ACTH syndrome [EAS]), and 1% are caused by corticotropin-releasing hormone (CRH)-secreting tumors." (PMID 34905486, 2021). "In addition, co-secretion of both CRH and ACTH in the same tumor cell of both pure pituitary adenoma and isolated GC have also been reported in patients with Cushing’s disease." (PMID 32706866, 2020). "Although CRH was not considered a stimulator of GH in mammals, a paradoxical increase of GH in response to CRH was observed in patients with pituitary adenomas and this is a topic under consideration in current research." (PMID 33708174, 2020). "In point of fact, a key feature of ACTH-secreting pituitary adenomas is that although ACTH secretion is autonomous, i.e., inappropriately high given excess cortisol levels, it remains sensitive to both CRH and strong negative feedback." (PMID 27220856, 2017). "Following the results of diagnostic performance analysis, in those patients with concordant positive responses to CRH test and HDDST but inconclusive neuroradiological findings (i.e., negative imaging or pituitary adenoma < 6 mm), the execution of BIPSS did not improve surgical outcome." (PMID 34699044, 2022). "It is important to realize that healthy volunteers could have increased inferior petrosal sinus-to-peripheral ratios, as they can have ACTH responses to CRH, that is, a positive inferior petrosal sinus sampling (IPSS) result is not sufficient to suggest that a pituitary adenoma is the etiology." (PMID 37260439, 2023).
mood disorder (18 papers, 2012 to 2025). A cognitive disorder a disturbance in which the person's mood is hypothesized to be the main underlying feature. "The summarized data presented in this review provide important insights into a role for CRH in mediating the maladaptive behaviors associated with major mood disorders and demonstrate the complexity of the underlying neurocircuitries involved in mediating CRH activity." (PMID 23077729, 2012). "We propose CRH-neutralizing antibodies and CRH-synthesis inhibitors as potential targets for reducing long-term cortisol in mood disorders and chronic stress." (PMID 39849227, 2025). "Despite the failure to date of the CRH antagonists in moving across the clinical trials pipeline, there is evidence for their beneficial effects beyond mood disorders." (PMID 35275963, 2022). "We identify two CRH-associated drug targets that are expected to lower long-term cortisol in chronic stress conditions and mood disorders but not in Cushing’s syndrome." (PMID 39849227, 2025). "Acyl ghrelin regulates the stress response by acting indirectly on corticotropin-releasing hormone (CRH) neurons in the paraventricular nucleus and directly at the anterior pituitary gland to facilitate ACTH release and to increases circulating ACTH to avoid mood disorder caused by its imbalance." (PMID 32565790, 2020). "Then, IL-1β induces the secretion of a corticotropin-releasing hormone (CRH) and the consecutive production of adrenocorticotropic hormone (ACTH), resulting in mood disorders." (PMID 38642324, 2025). "Then, IL-1β induces the secretion of CRH and the consecutive production of ACTH/glucocorticoids, resulting in mood disorders." (PMID 32076399, 2019). "Thus, we conclude that CRH-synthesis inhibitors or neutralizing antibodies cannot be compensated by the HPA axis, and are candidates to lower cortisol in mood disorders and in chronic stress." (PMID 39849227, 2025). "Although hypothalamic CRH neurons are activated in MDD and BD, and CRH production is increased in AD and mood disorders, no information is available about the possible involvement of PACAP in these disorders." (PMID 37226771, 2023). "IL-1β in turn induces the secretion of corticotropin-releasing hormone (CRH) and in consequence the secretion of adrenocorticotropic hormone (ACTH) and cortisol, which together with a plethora of further cytokines/chemokines lead to mood disorders." (PMID 32076399, 2019). "In addition, these studies implicate components of the CRH system as potential therapeutic targets for interventions aimed at treating the negative behavior sequelae of mood disorders." (PMID 23077729, 2012).
pheochromocytoma (17 papers, 2007 to 2026). "Ectopic simultaneous ACTH and CRH production can change the typical presentation of pheochromocytoma, impeding a diagnostic process." (PMID 41334448, 2025). "From the literature, the tumors most commonly associated with ectopic CRH production are medullary thyroid carcinoma, pheochromocytoma, and prostate cancer." (PMID 20807418, 2010). "To date, isolated ectopic CRH production has primarily been reported in cases of medullary thyroid carcinoma, pheochromocytoma, and various neuroendocrine tumors." (PMID 40927294, 2025). "ACTH and CRH expression in removed tumor characterized as pheochromocytoma was confirmed by immunohistochemistry." (PMID 41334448, 2025). "Although ACTH/CRH-secreting pheochromocytoma is extremely rare, timely recognition of this tumor is crucial." (PMID 41334448, 2025). "Isolated ectopic CRH production has primarily been described in cases of medullary thyroid carcinoma and pheochromocytoma." (PMID 40927294, 2025). "In rare cases, neuroendocrine tumors such as pheochromocytoma and medullary thyroid carcinoma produce corticotropin-releasing hormone (CRH), which then results in pituitary ACTH over-secretion." (PMID 36105398, 2022). "In this work, we performed single-cell RNA sequencing to three different anatomic tumor tissues and one peritumoral tissue based on a rare case with ectopic ACTH&CRH-secreting pheochromocytoma." (PMID 34905486, 2021). "Since the combination of dual ACTH/CRH secreting pheochromocytoma with CS is extremely rare, there is limited knowledge about the diagnosis and management of this disease." (PMID 34905486, 2021). "In this study, we reported a rare case of CRH/ACTH-secreting pheochromocytoma infiltrating the kidney and psoas muscle tissue." (PMID 34905486, 2021). "Lymphatic endothelial cells were found in the adjacent adrenal specimen of the rare ACTH+&CRH + pheochromocytoma (esPHEO_Adj)." (PMID 34905486, 2021). "The overexpression of PNMT was responsible for the significantly elevated epinephrine of the rare Case 1 with ectopic ACTH and CRH secretory pheochromocytoma." (PMID 34905486, 2021). "Because there are no sustentacular cells in ACTH&CRH secreting pheochromocytoma, ACTH&CRH secreting pheochromocytoma is more serious than the common pheochromocytoma." (PMID 34905486, 2021). "Overall, we reported a rare case in which ectopic ACTH&CRH-secreting pheochromocytoma on the left adrenal that infiltrated around the kidney and psoas major tissues." (PMID 34905486, 2021). "In this study, we reported an extremely rare patient (Case 1) with ATCH-dependent CS due to an ectopic ACTH&CRH secreting pheochromocytoma." (PMID 34905486, 2021). "Like ordinary pheochromocytomas and paragangliomas, most cases of composite pheochromocytomas or paragangliomas were functional, with increased levels of catecholamines or corticotropin-releasing hormone." (PMID 24779851, 2014). "Corticotropin-releasing hormone has also been shown to upregulate the expression of FasL in PC12 rat pheochromocytoma cells, by activating CRHR1." (PMID 17667919, 2007). "Corticotropin-releasing hormone is expressed in melanoma, pheochromocytoma, ovarian cancer and breast cancer." (PMID 17667919, 2007). "Ectopic ACTH or CRH changes the typical presentation of pheochromocytoma." (PMID 41334448, 2025). "The early presentation in ACTH/CRH-producing pheochromocytomas might be attributed to synergistic effects of glucocorticoids and catecholamines." (PMID 41334448, 2025). "Pheochromocytoma/paraganglioma accounted for about 5% of ectopic ACTH/CRH-secreting tumors." (PMID 41334448, 2025). "There have been rare reports of CS, extrapituitary in etiology but often difficult to distinguish from CD, resulting from ectopic production of corticotropin-releasing hormone (CRH), from pheochromocytomas, medullary thyroid cancers, and other neuroendocrine tumors." (PMID 37409236, 2023).
pheochromocytoma (continued). "Ectopic secretion hormones ACTH and CRH may complicate the presentation of pheochromocytoma, and this tumor usually leads to CS, which can be fatal if not properly diagnosed and managed." (PMID 34905486, 2021). "Although previous studies have reported ectopic ACTH and CRH secreting pheochromocytomas, it was unclear whether a unique cell type that produces multiple hormones influences CS." (PMID 34905486, 2021). "Therefore, no obvious genetic driver was found to explain the rare case of ACTH/CRH-secreting phaeochromocytoma." (PMID 34905486, 2021). "An endocrine rather than genetic association occurs when pheochromocytomas secrete hypothalamic-releasing hormones (GHRH or CRH) mimicking the PA and pheo/PGL syndrome, described previously in eight cases." (PMID 25494863, 2015). "Like ordinary pheochromocytoma/paraganglioma, most cases of composite pheochromocytoma/paraganglioma were functional, with increased level of catecholamines or corticotropin-releasing hormone (CRH) or their metabolites or whatever, and over 62% of the patients were also hypertensive." (PMID 23587063, 2013). "In addition, to investigate the genetic driver for Case 1, we supplemented whole-exome sequencing experiments for all rest specimens, that is, tumors (esPHEO_T2 and esPHEO_T3) and controls (esPHEO_Adj and esPHEO_Blood) from the rare case with ectopic ACTH&CRH-secreting pheochromocytoma." (PMID 34905486, 2021). "Hereby, we present a patient with pheochromocytoma secreting both ACTH and CRH, which is extremely rare." (PMID 41334448, 2025). "Pheochromocytoma can also produce other hormones such as interleukins, calcitonin, ACTH, or corticotropin-releasing hormone (CRH)." (PMID 41334448, 2025). "For instance, CRH has been reported inducing apoptosis in neurons, in PC12 rat pheochromocytoma cell line, in microglial cells, in prostate cancer cell RM-1 and in the mural granulosa cells (MGCs) of mouse ovarian follicles." (PMID 36497149, 2022). "Pheochromocytoma, a catecholamine-producing tumor, becomes even rarer when it is capable of both secreting ACTH and CRH." (PMID 34905486, 2021). "We did find that these markers were all positive in the tumor tissue, which further indicated that the special rare pheochromocytoma exhibited multiple hormone-secreting characteristics, including ACTH, CRH, and catecholamines." (PMID 34905486, 2021). "But so far, we have encountered only one case of pheochromocytoma secreting both ACTH and CRH, which was first reported in this study." (PMID 34905486, 2021). "Histopathological evaluation revealed a pheochromocytoma producing both ACTH and CRH." (PMID 41334448, 2025). "To date, only three cases of pheochromocytoma co-secreting ACTH and CRH have been documented." (PMID 41334448, 2025). "By 2020, only two cases with pheochromocytoma secreted both ACTH and CRH were reported." (PMID 34905486, 2021). "We found the heterogeneity of T cells in different adrenal tumor subtypes, that is, compared with CD4 T cells in adrenocortical adenomas, the pheochromocytoma types were mostly manifested by activated CD8+, especially in the anatomic specimens from the ectopic ACTH&CRH secreting pheochromocytoma." (PMID 34905486, 2021). "For comparison, other adrenal tumor subtypes were also collected and studied, namely, a common pheochromocytoma (without ectopic ACTH or CRH secretion function) and two adrenocortical adenomas." (PMID 34905486, 2021). "The ability of CRH to regulate cell apoptosis in several cells of different origin has been reported, and CRH has been shown to induce FASLG (Fas ligand) production and apoptosis in the rat pheochromocytoma cell line PC12 via activation of MAPK (p38 mitogen-activated protein kinase)." (PMID 23587111, 2013).
preeclampsia (17 papers, 2012 to 2026). Preeclampsia is a hypertensive disorder of pregnancy that is characterized by new-onset hypertension with proteinuria presenting after 20 weeks of gestation, and depending on mild or severe forms may initially present with severe headache, visual disturbances, and hyperreflexia. "Elevated levels of CRH are major risk factors for preterm birth, gestational hypertension, preeclampsia and PROM." (PMID 39959784, 2025). "Evidence suggests CRH inhibits immune rejection processes by killing activated T cells, plays an important role in determining time of parturition, and an increase in CRH has been associated with the onset of miscarriage and preeclampsia." (PMID 30940137, 2019). "Yet other studies have demonstrated relationships between placental CRH and risk for obstetric conditions, such as preeclampsia and pregnancy-induced hypertension, that, in turn, are predictive of extreme birth weight." (PMID 22984453, 2012). "Preeclampsia is characterized by abnormally high levels of placental-derived Corticotropin-Releasing Hormone (CRH), which leads to a state of chronic hypercortisolism followed by a precipitous “crash” in HPA axis activity after delivery of the placenta." (PMID 41517645, 2026). "Another potential route that phthalates can contribute to preeclampsia development is through inducing increased production of placental corticotropin-releasing hormone (CRH)." (PMID 40745234, 2025). "In a cohort of pregnant women exposed to phthalates, CRH was observed to be more highly expressed and correlated with the presence of gestational hypertension." (PMID 40745234, 2025). "In the hypoxic-ischemic environment of preeclampsia, a novel member of the CRH peptide family significantly increases Ucn2 and Ucn3, further promoting the response to oxidative stress in the placenta." (PMID 38894741, 2024). "Meanwhile, it is observed that in humans, hypoxia, stress, preeclampsia, eclampsia, and inflammatory cytokines lead to increased placental CRH secretion." (PMID 37363756, 2023). "In particular, certain stress-related biopsychosocial variables were related to preeclampsia, including change in corticotropin releasing hormone and hair cortisol levels measured at 12–21 weeks of pregnancy." (PMID 31568495, 2019). "CRH has been shown to be greatly elevated with preeclampsia, thus a possible explanation for this finding." (PMID 26334745, 2015). "Antonis Makrigiannakis suggested that corticotropin releasing hormone (CRH) may contribute to preeclampsia." (PMID 33335538, 2020). "The MPR group had the highest levels of CRH and the highest rate of preeclampsia." (PMID 26334745, 2015). "In comparison with the normal control group, the expression levels of the candidate genes ANKRD37, CRH, LEP, and SIGLEC6 in preeclampsia placenta were significantly increased, as visualized by the boxplot function." (PMID 38894741, 2024). "Preeclampsia placentas exhibited significantly elevated levels of NKRD37, CRH, LEP, and SIGLEC6 expression compared to the control group." (PMID 38894741, 2024). "In order to further understand the role of screened biomarkers in the diagnosis and prediction of preeclampsia, we based on the nomogram model of four key genes: ANKRD37, CRH, LEP, and SIGLEC6." (PMID 38894741, 2024). "From the heatmap, it can be observed that the expression of ANKRD37, CRH, LEP, and SIGLEC6 in preeclampsia placenta is significantly increased." (PMID 38894741, 2024). "Employing weighted gene co-expression network analysis (WGCNA) and lasso regression, four potential target genes (ANKRD37, CRH, LEP, SIGLEC6) are identified for potential prediction of preeclampsia." (PMID 38894741, 2024). "Studies have reported that corticotropin releasing hormone (CRH), PSG1 and CYP19A1 are directly related to the development preeclampsia." (PMID 33890634, 2021).
preeclampsia (continued). "For example, genes involved in hormone regulation (i.e., CGB, CRH, INHA, and GH2), which have been previously shown to be key in the maintenance of pregnancy, show substantial overlap in preeclampsia studies." (PMID 26044726, 2015). "qRT-PCR confirmed LEP and CRH increased, while SPP1 expression in preeclampsia samples." (PMID 39967661, 2025).